MALAT1 (metastasis associated lung adenocarcinoma transcript 1)
Diseases named in the same sentence as MALAT1 in open-access papers (continued):
Sharing a sentence is not in itself a finding about the gene and the disease.
tumor (continued). "Among the 40 patients, 24 were evaluable for lncRNA MALAT1 expression analysis in tumor tissue." (PMID 31827510, 2019). "TNC may promote ES tumour progression by targeting MALAT1 through integrin α5β1-mediated YAP activation." (PMID 31649319, 2019). "Besides, p‐MALAT1 greatly upregulated the expression of MALAT1, which was downregulated with si‐MALAT1‐1 in tumour tissues (**P < 0.01)." (PMID 31250518, 2019). "Regarding the role of MALAT1 in HCC, overexpression of MALAT1 in tumor tissues or sera may correlate with advanced tumor stages and reduced overall survival of HCC patients and indicate a higher risk of tumor recurrence following liver transplantation." (PMID 31500187, 2019). "MALAT1 promoted tumor growth by regulating the expression of miR-142-3p in vivo." (PMID 31168355, 2019). "Moreover, MALAT1 is considered to be a proto-oncogene in an increasing number of human tumor tissues." (PMID 31101802, 2019). "One example of successful in vivo analysis of ASO effectiveness is seen with systemic knockdown of MALAT1 using subcutaneous delivery of ASO in a mouse mammary tumour virus (MMTV) PyMT model; this caused primary tumours to differentiate and there was a significant reduction in metastases." (PMID 31336952, 2019). "Notably, g#5 reduced the growth of AMO-BZB-luc xenografts; on-target activity of g#5 in vivo was confirmed by reduced MALAT1 levels in resected tumor samples after g#5 treatment." (PMID 29487387, 2018). "A number of noncoding RNAs such as urothelial cancer associated 1 (UCA1), MALAT1, H19, and plasmacytoma variant translocation (PVT1) have been implicated in the promotion of metastasis of tumour cells, but evidence for a more direct role of these RNAs in this process is still lacking." (PMID 30296263, 2018). "Moreover, MALAT1 was also related with tumour size (pooled OR = 1.875, 95% CI 1.257–2.795, P = 0.002) and TNM stage (pooled OR = 2.034, 95% CI 1.111–3.724, P = 0.021)." (PMID 30093838, 2018). "Nude mice injected with cells transfected with si-MALAT1 had smaller tumor on size and weight." (PMID 30285605, 2018). "In addition, Malat1 was reported to play an important role in tumor-driven angiogenesis through regulating vasculature formation and fibroblast growth factor 2 expression." (PMID 29891768, 2018). "Importantly, lentiviral shRNA targeting of MALAT1 reduced tumor growth in vivo in xenograft models of arsenite-transformed HCC cells, strengthening the role of MALAT1 in carcinogen-induced tumorigenesis." (PMID 29739426, 2018). "MALAT1 undergoes a tight transcriptional control in tumor cells." (PMID 29739426, 2018). "Subsequent studies have shown that MALAT1 is aberrantly up-regulated in various tumor entities." (PMID 29495592, 2018). "Upregulated MALAT1 was shown in OS tissues as compared to para‐tumor tissues." (PMID 30094957, 2018). "MALAT1 might exert its tumor suppressor role by inactivation of the prosurvival ERK/MAPK signaling and/or enhance the expression of FBXW7, an antiproliferation protein." (PMID 30116729, 2018). "Moreover, hormones, such as oxytocin, or growth factors, such as TGF-β, can transcriptionally induce MALAT1 leading to tumor growth." (PMID 29739426, 2018). "Knockdown expression levels of MALAT1 inhibited tumor formation of the 22Rv1 cells in vivo." (PMID 30591689, 2018). "Thus, MALAT-1 promotes tumor growth and migration and prevents tumor cell apoptosis, linc-POU3F3 induces angiogenesis, ZFAS1 promotes proliferation and migration of cancer cells." (PMID 30211160, 2018). "Finally, NRF1 was found to bind to and transactivate MALAT1 promoter, providing evidence of a novel regulatory loop in MM cells, whose targeting by g#5 enhanced bortezomib anti-tumor activity both in drug sensitive and resistant MM cells." (PMID 29487387, 2018). "Importantly, the tumor formation assay in a nude mouse model demonstrated that MALAT1 had a similar effect on TMZ resistance in vivo." (PMID 29479863, 2018).
tumor (continued). "Therefore, different expression model of MALAT-1 and miR-200c-3p in human tumor entities needs further mechanism researches." (PMID 30352575, 2018). "We have previously found that the MALAT-1 promotes tumor growth and metastases in PDAC." (PMID 30352575, 2018). "Interestingly, tumor suppressor miR-101 and miR-217 acted as post-transcriptional regulators of MALAT1, whose silencing induced cell cycle arrest by p21 and p27 upregulation, and b-MYB inhibition." (PMID 29739426, 2018). "Our previous studies have revealed that MALAT-1 promotes tumor growth and metastases in PDAC." (PMID 30352575, 2018). "Furthermore, MALAT1 affected tumour cell anchorage-independent growth, and cells transfected with siMALAT1-1 or siMALAT1-2 siRNA displayed fewer and smaller colonies in soft agar than control cells." (PMID 28701723, 2017). "The expression level of MALAT1 was higher in ccRCC tissues compared to adjacent non-tumor tissues, and knocking down MALAT1 expression decreased ccRCC proliferation, migration and invasion, supporting its involvement in ccRCC tumorigenesis, as reported recently." (PMID 28812986, 2017). "MiR-217, a tumor suppressor, can inhibit MALAT-1 through the Ago2-mediated pathway, and thus inhibit EMT by suppressing EZH2-mediated H3K27me3, upregulating E-cadherin and downregulating N-cadherin and vimentin in cigarette smoke extract (CSE)-induced malignant transformation of HBE cells." (PMID 27992370, 2017). "Moreover, MALAT1 knockdown inhibits cell cycle progression and impairs tumour cell migration and invasion." (PMID 28701723, 2017). "Recently, the role of MALAT1 in tumor development has been extensively reported." (PMID 28412742, 2017). "Based on our clinical data, we focused on the role of MALAT1 in tumor invasion." (PMID 28077118, 2017). "For instance, the famous lncRNA MALAT1 was proven to indicate a hint of tumor metastasis." (PMID 28057064, 2017). "For instance, metastasis-associated lung adenocarcinoma transcript-1 (MALAT1) and lncRNA-activated by TGF-β (lncRNA-ATB) are upregulated in HCC tissues, while lncRNA low expression in tumor (lncRNA-LET) and lncRNA downregulated expression by HBx (lncRNA-Dreh) are downregulated in HCC." (PMID 28724429, 2017). "Recent publications reported that MALAT1 is a target of a number of tumor suppressor miRNAs, which could induce its degradation and suppress its oncogenic effects." (PMID 29147648, 2017). "Knockdown of MALAT1 in each of these tumor cell lines reduced the expression of SOX2." (PMID 28388544, 2017). "For example, MALAT1 or UCA1 could play important roles in facilitating genome-wide occupancy of EZH2 onto chromatin in tumor cells." (PMID 29050269, 2017). "Moreover, tumor growth in MALAT1++ group was markedly faster than that in MALAT1- group in the following 24 days after injection." (PMID 28938647, 2017). "Furthermore, a reciprocal effect between MALAT1 and miRNA-205, a tumour suppressor in RCC, was observed." (PMID 27092491, 2016). "Animal experiments showed that knockdown of MALAT1 decreased tumor formation and improved survival." (PMID 27015363, 2016). "These correlation analyses in patient samples imply that MALAT1 could potentially regulate the expression of key genes involved in tumor progression and/or metastasis in BC cells of specific subtype or of different LN status." (PMID 27250026, 2016). "MALAT1 mRNA was found exclusively in the nucleus of both stromal and tumour epithelial cells." (PMID 27172249, 2016). "Over-expression of MALAT1 was most frequently in advanced stage tumor samples." (PMID 27686732, 2016).
tumor (continued). "Results confirmed that MFS of patients with low Δsv-MALAT1-expressing tumours (5-year RFS 70.3±2.5% 10-year RFS 58.5±2.8% 15-year RFS 51.4±3.0%) was shorter than that of patients whose tumours highly expressed Δsv-MALAT1 (5-year RFS 85.9±3.5% 10-year RFS 82.3±3.9% 15-year RFS 76.0±5.1% P=0.000015)." (PMID 27172249, 2016). "It is possible that differential levels of MALAT1 in various subtypes of BC could also be attributed to various cell types from where the tumor is derived." (PMID 27250026, 2016). "Two studies claimed that up-regulated RCCRT1 and MALAT1 were significantly related to tumor size." (PMID 27527868, 2016). "In addition to the mentioned molecular insights, high levels of MALAT1 are significantly correlated with tumour size, pathologic T-stage, as well as lymph node metastases." (PMID 27092491, 2016). "However, our functional analyses in different BC cell lines illustrate that the role of MALAT1 in tumor progression is not limited to luminal subtype; rather MALAT1 is also actively involved in the tumor progression in other BC subtypes, including TNBC cells." (PMID 27250026, 2016). "MALAT1 is thought to regulate tumor cell viability, invasiveness and migration." (PMID 27777857, 2016). "MALAT1 expression was higher in tumor tissues compared with adjacent non-tumor tissues." (PMID 27458156, 2016). "In general, the expression of MALAT1 is higher in cancerous tissue compared to normal tissue with enhancement of cell proliferation, apoptosis, migration, invasion and metastatic spread of tumour cells." (PMID 27092491, 2016). "Thus, our results support the potential use of monitoring MALAT1 level as a prognostic predictor of tumor recurrence and metastasis in patients diagnosed with ER negative lymph node negative BC." (PMID 27250026, 2016). "This implies that MALAT1 might play a crucial role in tumor progression in luminal subtype over TNBC subtype." (PMID 27250026, 2016). "Indeed, Δsv-MALAT1 expression varied widely in tumour tissues, being both underexpressed (18.8%) and overexpressed (5.4%)." (PMID 27172249, 2016). "This supports our hypothesis that MALAT1 plays an active role in regulating tumor progression and metastasis in TNBC cells." (PMID 27250026, 2016). "In addition, similar results were obtained from correlation analysis among the expression levels of RBM24, miR-25, and MALAT1 in the primary NPC fresh tumor tissues." (PMID 27584791, 2016). "They identified MALAT1 expressed threefold higher in metastatic tumor tissues." (PMID 27143813, 2016). "Thirty GBC patients were classified into two groups depending on their Malat1 levels in tumor tissues relative to the median ratio (3.31): high-Malat1 group (n = 15, Malat1 expression ratio ≥ median ratio); and low-Malat1 group (n = 15, Malat1 expression ratio < median ratio)." (PMID 27191262, 2016). "As a typical tumor marker, Malat1 expresses with high level in malignant cells." (PMID 26335021, 2015). "Additionally, using orthotopic tumor models in nude mice, it was found that MALAT1 induction resulted in a significant increase of tumor metastatic potential." (PMID 26064090, 2015). "We also found that amplification of MALAT1 in tumor tissues may partially contribute to its over-expression, but the genomic amplification in somatic tissues should be a complex event, instead of being derived from a germline source." (PMID 25613496, 2015). "Furthermore, they described a significant correlation between MALAT1 expression levels and tumor size, tumor stage, invasion, and disease-free survival." (PMID 25910082, 2015). "In ESCC tissues, MALAT1 expression was negatively associated with phosphorylation of the ATM-CHK2 pathway, suggesting over-expression of MALAT1 may contribute to rapid tumor growth by suppressing cell cycle arrest." (PMID 25613496, 2015). "Similarly, down-regulation of MALAT1 in cell lines of different tumor types inhibits tumor growth in in vivo models using tumor xenografts in nude mice." (PMID 26516918, 2015).
tumor (continued). "There is a lot of evidence suggesting that MALAT1 may be involved in cell cycle regulation, which may contribute to uncontrolled tumor growth." (PMID 25613496, 2015). "In total, our results highlighted the importance of MALAT1 in ATM-CHK2 pathway regulation, which may help us to interpret the mechanisms on how MALAT1 regulates tumor growth from a new perspective." (PMID 25613496, 2015). "MALAT1 was originally shown to control of tumour metastasis and cancer cell survival." (PMID 25787249, 2015). "Additionally, MALAT1 expression levels were positively correlated with tumor size, stage, and depth of invasion and the overexpression of MALAT1 was independently associated with poorer disease-specific survival of PDAC patients." (PMID 26064090, 2015). "More importantly, targeting MALAT1 inhibited TSCCA cell-induced xenograft tumor growth in vivo." (PMID 26522444, 2015). "In this study, our data showed that MALAT-1 could increase the proportion of pancreatic CSCs, maintain self-renewing capacity, decrease the chemosensitivity to anticancer drugs, and accelerate tumor angiogenesis in vitro." (PMID 25811929, 2015). "To investigate MALAT-1 expression whether affect in vivo biological function, we detected Ki67 expression for tumor cell proliferation and CD31 for angiogenesis by immunohistochemistry." (PMID 25811929, 2015). "Because MALAT1 might promote OSCC tumor growth in vivo, it may serve as a therapeutic target for treatment." (PMID 26522444, 2015). "Surprisingly, we found no copy number gain in germline samples, indicating that the CNV status may differ in diverse ethnic groups, and it is hard to predict whether the amplification of MALAT1 in tumor tissues came from the germline origin." (PMID 25613496, 2015). "Together, these findings suggest that MALAT1 participates in the progression of NSCLC and that overexpression of MALAT1 can be used as an indicator to identify whether the tumour has the potential for metastasis." (PMID 25297942, 2014). "Finally, downregulation of the lncRNA MALAT-1 delayed tumor growth in vivo and reduced metastasis of PCa xenografts in castrated male nude mice." (PMID 25250334, 2014). "Regarding the fourth key characteristic of diagnostic biomarkers, the results indicate that MALAT1 values in blood are not correlated with tumor size, metastasis status, or lymph node status." (PMID 24313945, 2013). "Furthermore, we demonstrated that ZIC1 can suppress the expression of other novel genes (TACSTD2, ANGPT2, LAMB2, LAMB3 and MALAT1 etc.)related to tumor angiogenesis and metastasis." (PMID 21347233, 2011). "For example, MALAT1 plays a role in the regulation of splicing factors such as SR proteins (serine/arginine‐rich proteins) and has been shown to alter the splicing patterns of various mRNAs, thereby impacting gene expression profiles that drive tumor cell proliferation and migration." (PMID 40231344, 2025). "However, it remained unclear whether there were miRNAs in the downstream regulation of tumor-promoting signaling of NCAPD3-mediated MALAT1 and TFs in PCa." (PMID 38561330, 2024). "MALAT1 may inhibit tumor growth and metastasis through PI3K/AKT signaling pathway." (PMID 39015175, 2024). "This shows that MALAT-1 may be essential for developing tumor cells in CC." (PMID 38511067, 2024). "However, in contrast, MALAT1 may have a tumor-suppressive function in glioma cells through inactivation of MAPK-signaling." (PMID 37235843, 2023). "Thus,it has been established that MALAT1 plays a critically important role in theregulation of transcription and the cell cycle, epigenetic regulation, as wellas in the inflammation and metastatic processes in tumor." (PMID 37538803, 2023). "Importantly, ASO targeting MALAT1 was effective in inhibiting HCC tumor growth in vivo." (PMID 37653482, 2023).
tumor (continued). "Finally, the comparison of MALAT1 associated pathways and the involved genes showed a low degree of overlapping in the corresponding gene signatures, even in cell cycle-related or MAPK pathways that were initially observed as enriched in both neoplasms." (PMID 37803049, 2023). "Given its potential role in immune evasion and inflammation, a deeper understanding of MALAT1 function could elucidate the intricacies of tumor–stroma immune interaction via exosomes in CRC, possibly paving a way for novel therapeutic strategies that target the NF-κB signaling pathway." (PMID 37760852, 2023). "However, this tumor suppression function of miR-202 can be perturbed by the upstream regulatory circuitry involving the production of the lncRNA MALAT1 or other upstream regulators/oncogenes, which varies according to tissue type and eventually tumor stage and type." (PMID 35682549, 2022). "Thus, MALAT1 can act as a tumor biomarker and therapeutic target." (PMID 36163080, 2022). "Therefore, MALAT1 can be considered as a tumor biomarker in diagnosing and treating PC." (PMID 36163080, 2022). "Transient transfection of MM cell lines with anti-MALAT1 short hairpin RNAs (shRNAs) halts cell cycle in G1 phase, induces apoptosis by modulating the pro-apoptotic Bax and the anti-apoptotic Bcl-2 proteins in vitro, and reduces tumor growth in xenografted mice." (PMID 35454868, 2022). "Interestingly, HOTAIR and MALAT1 are known to be the master regulators of tumor progression." (PMID 36387279, 2022). "In addition, MALAT1 expression was adversely correlated to SOX17 expression in tumor tissues." (PMID 35614065, 2022). "Besides, we examined the expression of MALAT1 in mouse tumor." (PMID 35557985, 2022). "MALAT1 could also aid in increasing the proportion of pancreatic CSCs, maintaining the self-renewal abilities of cells, inducing chemoresistance, and promoting tumor angiogenesis." (PMID 35565245, 2022). "The lncRNA MALAT-1 (metastasis-associated lung adenocarcinoma transcript 1), for example, is substantially expressed in patients suffering from non-small-cell lung cancer (NSCLC), and that of exosomal MALAT-1 is linked to the tumor, node, and metastasis (TNM) stage." (PMID 35886037, 2022). "In addition, miR-211 could sponge lncRNA MALAT1 to suppress tumor growth and progression through inhibiting PHF19 in OC." (PMID 33413565, 2021). "Τhis observation, combined with the lack of DNAse treatment, may explain the ambiguous results of various studies that characterized MALAT1 either as oncogene or as tumor suppressor and consequently report that its expression is upregulated or downregulated, respectively." (PMID 34202021, 2021). "In addition, Jen and colleagues revealed a new mechanism whereby Oct4 transcriptionally activates lncRNAs, NEAT1 and MALAT1, via promoter and enhancer-binding, respectively, to promote tumor cell proliferation and metastasis, leading to lung tumorigenesis and poor prognosis." (PMID 33627711, 2021). "However, in colon and BC, tumor-suppressive role of MALAT1 has been discovered." (PMID 33522932, 2021). "Therefore, the expression level of MALAT1 is an important prognostic factor for tumor patients." (PMID 33691715, 2021). "In addition to rs3200401, MALAT1 rs619586 polymorphisms presented significant differences in terms of clinical stage (AOR: 1.358-fold; 95% CI: 1.009~1.827; p=0.044) and tumor size (AOR: 1.429-fold; 95% CI: 1.064~1.919; p=0.018) in OSCC patients with at least one minor allele (AG or GG)." (PMID 34268119, 2021). "MALAT1 might function regulating immune cell infiltrating in tumor microenvironments." (PMID 34308750, 2021). "However, the role of miR-188-5p in the MM and whether miR-188-5p mediates the MM tumor progression regulated by MALAT1 are still unknown." (PMID 33944676, 2021). "Furthermore, expression of MALAT1 was related to tumor immune cell infiltrating." (PMID 34308750, 2021).